ACKR1 (atypical chemokine receptor 1 (Duffy blood group))
Description:
Atypical chemokine receptor that controls chemokine levels and localization via high-affinity chemokine binding that is uncoupled from classic ligand-driven signal transduction cascades, resulting instead in chemokine sequestration, degradation, or transcytosis. Also known as interceptor (internalizing receptor) or chemokine-scavenging receptor or chemokine decoy receptor. Has a promiscuous chemokine-binding profile, interacting with inflammatory chemokines of both the CXC and the CC subfamilies but not with homeostatic chemokines. Acts as a receptor for chemokines including CCL2, CCL5, CCL7, CCL11, CCL13, CCL14, CCL17, CXCL5, CXCL6, IL8/CXCL8, CXCL11, GRO, RANTES, MCP-1 and TARC. May regulate chemokine bioavailability and, consequently, leukocyte recruitment through two distinct mechanisms: when expressed in endothelial cells, it sustains the abluminal to luminal transcytosis of tissue-derived chemokines and their subsequent presentation to circulating leukocytes; when expressed in erythrocytes, serves as blood reservoir of cognate chemokines but also as a chemokine sink, buffering potential surges in plasma chemokine levels. (Microbial infection) Acts as a receptor for the malaria parasite Plasmodium vivax. (Microbial infection) Acts as a receptor for the malaria parasite Plasmodium knowlesi.
Synonyms: GpFy; CD234; DARC; FY; GPD; CCBP1; Dfy; DARC/ACKR1; WBCQ1
Tractability: Small molecule: it belongs to a druggable protein family. Antibody: its Gene Ontology location is reachable by antibodies, with high confidence; UniProt predicts a signal peptide or a membrane-spanning region.
Target class: Chemokine receptor; Family A G protein-coupled receptor; Peptide receptor (family A GPCR); Membrane receptor
Gene: Protein-coding gene on chromosome 1 (159,204,568 to 159,206,500, forward strand). Ensembl gene ENSG00000213088.
Subcellular location: Early endosome; Recycling endosome; Membrane
Pathways (Reactome):
Signal Transduction: Peptide ligand-binding receptors
Gene Ontology:
Molecular function: C-C chemokine binding; chemokine receptor activity; signaling receptor activity; transmembrane signaling receptor activity; chemokine binding
Biological process: defense response; inflammatory response; regulation of chemokine production; chemokine-mediated signaling pathway
Cellular component: G protein-coupled receptor complex; plasma membrane; early endosome; membrane; recycling endosome
Genetic constraint (gnomAD): Loss-of-function variants: 4 observed, 3.93 expected, observed/expected ratio (o/e) 1.02, 90% interval 0.48 to 1.84. That is too few expected variants to judge how well the gene tolerates losing a copy. Missense variants: 438 observed, 416.53 expected, observed/expected ratio (o/e) 1.05, 90% interval 0.97 to 1.14. Synonymous variants: 208 observed, 188.85 expected, observed/expected ratio (o/e) 1.1, 90% interval 0.98 to 1.24.
Homologues: Orthologues: chimpanzee ACKR1 (99% identical), macaque ACKR1 (92% identical), guinea pig ACKR1 (64% identical), dog ACKR1 (63% identical), pig ACKR1 (62% identical), rat Ackr1 (60% identical), mouse Ackr1 (59% identical).
Diseases named in the same sentence as ACKR1 in open-access papers:
ACKR1 is named in the same sentence as 116 diseases in open-access papers, as found by Europe PMC text mining. Sharing a sentence is not in itself a finding about the gene and the disease. The quoted sentences say what the papers report.
malaria (55 papers, 2007 to 2025). Malaria is a serious and sometimes fatal disease caused by a parasite that commonly infects a certain type of mosquito which feeds on humans. "ACKR1, also known as the Duffy antigen receptor, was initially discovered on erythrocytes and loss of expression is associated with malaria resistance." (PMID 41258098, 2025). "We found that all Bubi individuals possessed the malaria-resistant allele of the ACKR1 and CD36 genes, in addition to certain variations in other genes such as G6PD, ATP2B4, GRK5, and IL-10." (PMID 30841922, 2019). "In addition to being the receptor for the parasite causing malaria, ACKR1 has been postulated to regulate innate immunity by displaying and trafficking chemokines." (PMID 37153544, 2023). "Intriguingly, a homozygous mutation in a GATA motif in the promoter region causes loss of ACKR1 expression on erythrocytes and confers protection from malaria but leaves endothelial ACKR1 expression unaffected." (PMID 37153544, 2023). "The extracellular domain of ACKR1 is a potential target to inhibit pathogenicity mechanisms of atypical malaria, S. aureus, and HIV." (PMID 37006247, 2023). "A unique selective pressure from malaria parasites contributes to distinct population-specific and geographic patterns of ACKR1 expression." (PMID 37006247, 2023). "There is in fact evidence that a strong selective pressure for malaria resistance in the Ethiopian population correlates with the development and maintenance of certain ACKR1 haplotypes." (PMID 35273596, 2022). "Mutations in ACKR-1, otherwise known as DARC, confer protection against malaria and are highly prevalent amongst AAs and other persons of color, including Hispanic Caucasians." (PMID 34733899, 2021). "Mutations in atypical chemokine receptor 1 (ACKR1), otherwise known as the Duffy antigen receptor for chemokines (DARC), confer protection against malaria." (PMID 34733899, 2021). "We collected blood samples from 60 individuals from Gambela, a tropical malaria-endemic region of southwestern Ethiopia, and sequenced a 5178-nucleotide region of chromosome 1 encompassing the ACKR1 gene." (PMID 30245840, 2018). "The existence of a strong selective pressure for malaria resistance implies that the Ethiopian population has a propensity to develop and maintain distinct malaria-resistant ACKR1 haplotypes." (PMID 30245840, 2018). "Willy Flegel at the National Institutes of Health, Bethesda, USA, and co-workers sequenced ACKR1 in 60 people from Gambela, Ethiopia, where malaria is endemic." (PMID 30245840, 2018). "This insertion may also have implications for some physiological roles of ACKR1 and be of interest in malaria research and population genetics." (PMID 41172681, 2025). "We hypothesized that admixture has facilitated rapid adaptation to the malaria parasite Plasmodium vivax via the malaria-protective Duffy antigen receptor for chemokines (DARC) locus (also known as Atypical Chemokine Receptor 1 [ACKR1]) in Santiago." (PMID 33393457, 2021). "Previous population-based molecular studies on the malaria resistance-associated ACKR1 gene have been centered in sub-Saharan African22,39 and North African Arab populations." (PMID 30245840, 2018). "We determined the haplotypes of the ACKR1 gene in a population inhabiting a malaria-endemic area." (PMID 30245840, 2018). "Duffy antigens, a component of blood type, are encoded by the ACKR1 gene, and individuals with the Duffy-negative blood type are resistant to malaria." (PMID 30245840, 2018). "The Duffy antigen, also known as DARC (Duffy antigen receptor for chemokines) and more recently as ACKR1 (atypical chemokine receptor 1), is a transmembrane receptor used by Plasmodium vivax, a malaria-causing protozoan, to infect red blood cells." (PMID 28282382, 2017).
malaria (continued). "However most of the low correlation SNPs pairs (80% of the shared loci with a rho < 0.8) were located on chromosome 1 near the ACKR1 locus (Chromosome 1: 159,204,875–159,206,500 forward strand), which is known to be adaptive to overcome p.vivax induced malaria." (PMID 38627641, 2024). "The atypical chemokine receptor 1 (ACKR1), formerly known as Duffy antigen receptor for chemokines (DARC), is a minor blood group antigen that functions as both a chemokine receptor and a receptor for the malaria parasite P. vivax." (PMID 35946633, 2022). "We identified long-range haplotypes and variations of the ACKR1 gene, including potential regulatory elements, without ambiguity, in an autochthonous population from a malaria-endemic area." (PMID 30245840, 2018). "Individuals lacking expression of the atypical chemokine receptor 1 (ACKR1), formally referred to as DARC (Duffy blood group antigen receptor for chemokines) are for example resistant to malaria." (PMID 35273596, 2022).
breast carcinoma (21 papers, 2012 to 2025). "The low expression of ACKR1 in breast cancer is strongly associated with intense tumor angiogenesis, ER status, lymph node metastasis, distant metastasis, and poor survival." (PMID 37108425, 2023). "There is abundant evidence to suggest that ACKR1 polymorphisms are associated with some diseases, such as chronic periodontitis, breast cancer and Plasmodium vivax malaria." (PMID 28443566, 2017). "Multiple studies have indicated that higher ACKR1 expression levels in breast cancer tumors improve relapse-free patient survival, while loss of ACKR1 expression, frequently in patients with African ancestry, is an indicator of increased tumor aggressiveness, metastatic propensity, and mortality." (PMID 37006247, 2023). "Moreover, the rs12075 polymorphism in ACKR1 has been linked to worse relapse-free survival in patients with triple-negative breast cancer and lymph node metastasis in patients with breast cancer." (PMID 37108425, 2023). "Studies suggesting a role for pro-angiogenic ACKR-1 binding chemokines in the pathogenesis of prostate and breast cancer provide a mechanistic basis for how the loss of expression of ACKR-1 on RBC might promote tumor growth." (PMID 34733899, 2021). "For ER+ breast cancer, the selection criteria revealed eight cell types: iCAF, myCAF, cancer luminal A, macrophages, ACKR1+ ECs, differentiated PVLs, CD4+ T cells and CD8+T cells." (PMID 41188599, 2025). "For ER+ breast cancer, the selection criteria revealed 8 cell types: iCAF, myCAF, cancer luminal A, macrophages, ACKR1+ endothelial cells, differentiated PVLs, CD4+ T cells, and CD8+ T cells (8×8=64 possible source/target cell combinations)." (PMID 39483921, 2024). "MDA-MB-231 breast adenocarcinoma cells were used to represent aggressive breast cancer with low endogenous ACKR1 expression, and MDA-MB-435 melanoma cells were used to model an ACKR1-expressing tumor." (PMID 37006247, 2023). "RNA count expression plotting for the TCGA breast cancer cohort only confirmed a significant decrease in ACKR1 expression in Asian compared to White and to Black patients." (PMID 35754051, 2022). "ACKR1 can inhibit breast cancer growth and progression by sequestration of angiogenic chemokines and subsequent inhibition of tumor neovascularity." (PMID 35754051, 2022). "In ER+ breast cancer, ACKR1+ endothelial cells had 15-fold increased homotypic interactions and significantly more interactions with various cell populations in the younger cohort, aligning with their enhanced protein secretion, and metabolic activity ARPs in younger patients." (PMID 39483921, 2024). "Besides, ACKR3 was scarcely expressed, and ACKR1 was expressed in a subset of endothelial cells in breast cancer." (PMID 37564657, 2023). "In this cancer, expression of ACKR2 was accompanied by ACKR1 and ACKR4 which were negatively correlated to axillary lymph node metastasis of breast tumor cells, suggesting favorable outcomes for co-expression of ACKR2, DARC, and CCX-CKR in breast cancer." (PMID 35677043, 2022).
neutropenia (18 papers, 2008 to 2026). A decrease in the number of neutrophils found in the blood. "This condition is known as ADAN (ACKR1/DARC-associated neutropenia) and synonyms include DANC (Duffy-null associated neutrophil count) and BEN (benign ethnic neutropenia)." (PMID 42125771, 2026). "Additionally, the Duffy-null genotype, a variant in the ACKR1 gene, is associated with lower neutrophil counts in African individuals and can lead to benign ethnic neutropenia, often mistaken for drug-induced neutropenia." (PMID 38921968, 2024). "We also replicated other previously reported African population-specific associations, such as ACKR1 for neutropenia and reduced white blood count levels and a missense variant, rs73885319 in APOL1 with kidney-related conditions such as end-stage renal disease." (PMID 37425708, 2023). "Benign neutropenia, which helps account for lower frequencies of neutrophils and higher lymphocyte counts in the circulation of Black individuals, has been associated with the rs2814778 (G) variant of the gene encoding atypical ACKR1, the Duffy antigen receptor for cytokines." (PMID 37606045, 2023). "Moreover, ACKR1-expressing nucleated erythroid cells are described to contribute to the regulation of hematopoiesis in the bone marrow, establishing a link between neutropenia and a specific ACKR1 gene variant causing the Duffy-negative phenotype." (PMID 36725964, 2023).
liver fibrosis (9 papers, 2017 to 2024). "In order to enrich the knowledge of this field, we aimed to investigate the association between ACKR1 polymorphism and liver fibrosis progression with HA, LN, C-IV and PIIINP." (PMID 29142552, 2017). "The aim of this study was to investigate the association between ACKR1 polymorphism and liver fibrosis with these four serum liver markers in HCV positive patients." (PMID 29142552, 2017). "This study has attempted to elucidate the role of ACKR1 polymorphism in liver fibrosis progression of HCV infection, but our results demonstrated that ACKR1 polymorphism is not directly associated with the fibrogenesis in HCV positive patients by using non-invasive serum liver related markers." (PMID 29142552, 2017). "Application of scRNA-seq method, TREM2+CD9+ macrophages and ACKR1+PLVAP+ endothelial cells were identified and expanded in liver fibrosis." (PMID 35791909, 2022). "This study has attempted to elucidate the role of ACKR1 polymorphism in liver fibrosis progression of HCV infection, our results demonstrated that ACKR1 polymorphism is not directly associated with the fibrogenesis in HCV positive patients." (PMID 29142552, 2017).
atherosclerosis (6 papers, 2019 to 2023). A disease characterized by the build-up of fatty material and calcium deposition in the arterial wall resulting in partial or complete occlusion of the arterial lumen. "In an atherosclerosis mouse model, knocking out ACKR1 led to diminished plaque formation, cellular infiltrate in the vessel walls, and activation of macrophages." (PMID 37006247, 2023). "ACKR1 involvement and targeting to treat atherosclerosis was initially proposed because endothelial dysfunction and chemokines like CXCL8 immobilized on erythrocyte membranes contribute to plaque formation and coronary artery disease." (PMID 37006247, 2023). "In cardiovascular diseases, the protein expressed by ACKR1 gene may destroy the barrier function of endothelial cells by promoting the aggregation and transfer of endothelial cells, and promote circulating leukocytes to enter the vascular intima at the early stage of atherosclerosis." (PMID 37207221, 2023).
COVID-19 (6 papers, 2021 to 2024). A disease caused by infection with severe acute respiratory syndrome coronavirus 2. "We study the prevalence and impact of autoantibodies on vascular dysfunction in healthy COVID-19 survivors, revealing elevated anti-ACKR1 autoantibodies associating with systemic cytokines and endothelial dysfunction." (PMID 38740432, 2024). "The blocking peptide uncovered that purified IgG from COVID-19 survivors possessed potential epitopes in the N-terminal extracellular domain of ACKR1, which effectively averted antibody-dependent cellular cytotoxicity." (PMID 38740432, 2024). "Focusing on autoantibodies against the atypical chemokine receptor 1 (ACKR1), COVID-19 survivors demonstrated significantly elevated anti-ACKR1 autoantibodies, correlating with systemic cytokines, circulating damaged endothelial cells, and endothelial dysfunction." (PMID 38740432, 2024).
glioma (5 papers, 2013 to 2022). A benign or malignant brain and spinal cord tumor that arises from glial cells (astrocytes, oligodendrocytes, ependymal cells). "We also depict various chemokine/receptor axes, such as CXCL8-CXCR1/2, CXCL12-CXCR4, CXCL16-CXCR6, CX3CL1-CX3CR1, CCL2-CCR2, and CCL5-CCR5 of special importance in gliomas, as well as atypical chemokine receptors ACKR1-4, CCRL2, and PITPMN3." (PMID 32456359, 2020).
Obesity (5 papers, 2012 to 2025). Accumulation of substantial excess body fat. "Global ACKR-1 knockout mice exhibit enhanced susceptibility to diet induced-obesity/adipose tissue inflammation and increased severity of prostate cancer compared with wild-type mice, which is in line with clinical data in African Americans vs. Caucasians." (PMID 34733899, 2021). "In this narrative review, we present the evidence regarding obesity-related disparities in the bidirectional risk of CVD and cancer and also discuss the potential association of gene polymorphisms in AAs with emphasis on ACKR1." (PMID 34733899, 2021).
lymph node metastasis (4 papers, 2013 to 2021). "In addition, a recent co-expression network analysis of the atypical chemokine receptor 1 (ACKR1) showed an ACKR1 was negatively correlated with lymph node metastasis and prognosis in cervical cancer." (PMID 34833360, 2021).
melanoma (4 papers, 2016 to 2023). A malignant, usually aggressive tumor composed of atypical, neoplastic melanocytes. "Overexpression of the endothelial ACKR1 in mice implanted with melanoma tumors demonstrated inhibition of tumor growth and vascularity and showed an increase in CD4+ and CD8+ T-cell and macrophage infiltration." (PMID 37006247, 2023).
Sepsis (4 papers, 2009 to 2023). Sepsis is defined as life-threatening organ dysfunction caused by a dysregulated host response to infection. "In addition, we observed broad interactions between KC_Cxcl10/KC_Cd5l and Hep/Endo through chemokines (including Cxc and Cc subfamilies) and the receptor Ackr1 in response to sepsis." (PMID 37808269, 2023).
cervical cancer (3 papers, 2021 to 2025). A primary or metastatic malignant neoplasm involving the cervix. "For example, genes like APOD, ACKR1, and SFRP4 have been recognized as significant in cervical cancer, and our analysis supports their involvement in tumor progression and patient survival, thereby reinforcing their potential as biomarkers in clinical practice." (PMID 40678068, 2025).
gastric cancer (3 papers, 2022 to 2025). A primary or metastatic malignant neoplasm involving the stomach. "In addition, we found ACKR1 specifically expressed in tumor endothelial cells, associated with poor prognosis in the cohort data and potentially provided a novel target of gastric cancer treatment." (PMID 35664061, 2022). "In the TCGA dataset, gastric cancer patients with high expression of ACKR1 gene had poor prognosis." (PMID 35664061, 2022).
mastitis (3 papers, 2016 to 2024). Inflammation of breast tissue during lactation or postpartum due to an obstructed duct or infection. "ACKR1 has been shown to be related to mastitis, as it was found to be differentially expressed in comparison with healthy udder tissue in other studies." (PMID 39333243, 2024). "This was followed by ACKR1, MT2A, and S100A12, which are associated with mastitis and mastitis response." (PMID 39333243, 2024). "As previously reported in other tissues, CXCL1 (KC), CXCL2 (MIP2), ICAM-1, ACKR1, Selp (P-selectin), and Itgam (Cd11b), are all most probably involved in transendothelial neutrophil trafficking in mastitis." (PMID 37032878, 2023). "Some immune-related genes, such as ITGB6, MYD88, ADA, ACKR1, and TNFRSF1B, and their potential relationships with mastitis were highlighted." (PMID 27459697, 2016).
endometriosis (2 papers, 2020 to 2022). The growth of functional endometrial tissue in anatomic sites outside the uterine body. "ACKR1, LMNB1, MFAP4, NMU, and SEMA3C were upregulated in ectopic endometrial tissues of patients with endometriosis compared with normal endometrium (P < 0.001), which was consistent with the results of bioinformatics analysis." (PMID 36277723, 2022). "Q RT-PCR was used to detect the expression of ACKR1, LMNB1, MFAP4, NMU, and SEMA3C mRNA in ectopic endometrial tissues of patients with endometriosis." (PMID 36277723, 2022).